FOXD4L1 (forkhead box D4 like 1)
Synonyms: FOXD5; bA395L14.1
Tractability: No criterion of Open Targets' tractability assessment is met for any kind of drug.
Gene: Protein-coding gene on chromosome 2 (113,498,665 to 113,501,150, forward strand). Ensembl gene ENSG00000184492.
Subcellular location: Nucleus
Subcellular location (Human Protein Atlas): Nucleoplasm; Cytosol
Gene Ontology:
Molecular function: protein binding; DNA-binding transcription factor activity, RNA polymerase II-specific; RNA polymerase II cis-regulatory region sequence-specific DNA binding; DNA-binding transcription factor activity; sequence-specific DNA binding
Biological process: anatomical structure morphogenesis; cell differentiation; regulation of transcription by RNA polymerase II; regulation of DNA-templated transcription
Cellular component: chromatin; nucleus
Genetic constraint (gnomAD): Loss-of-function variants: 10 observed, 21.23 expected, observed/expected ratio (o/e) 0.47, 90% interval 0.29 to 0.8. The synonymous counts are far from expectation, so gnomAD's model fits this gene poorly and the ratio says little. Missense variants: 364 observed, 493.81 expected, observed/expected ratio (o/e) 0.74, 90% interval 0.68 to 0.8. Synonymous variants: 159 observed, 215.9 expected, observed/expected ratio (o/e) 0.74, 90% interval 0.65 to 0.84.
Homologues: Orthologues: macaque FOXD4L1 (76% identical), mouse Foxd4 (59% identical). Paralogues in human: FOXD4 (74% identical), FOXD4L3 (72% identical), FOXD4L4 (72% identical), FOXD4L5 (72% identical), FOXD4L6 (72% identical), FOXD1 (35% identical), FOXD2 (35% identical), FOXD3 (32% identical), FOXE3 (25% identical), FOXC2 (25% identical), FOXC1 (24% identical), FOXE1 (23% identical), and 29 more.
Diseases named in the same sentence as FOXD4L1 in open-access papers:
FOXD4L1 is named in the same sentence as 3 diseases in open-access papers, as found by Europe PMC text mining. Sharing a sentence is not in itself a finding about the gene and the disease. The quoted sentences say what the papers report.
breast carcinoma (1 paper, 2023). "FOXD4 and FOXD4‐Like genes (FOXD4L1, etc.)were significantly co‐expressed in 6 cancers, mostly in breast cancer, but not in their corresponding normal tissues." (PMID 37401400, 2023).
tumor (2 papers, 2014 to 2023). "Among the 5,291 coding somatic mutations found in an aggregate of 240 matched tumour/normal samples, we found 26 overlapping variants in SH-SY5Y inside 24 genes among which 9 were rare amino-acid changing mutations inside 7 genes (ALK, FOXD4L1, HLA-DRB1, NBPF10, NBPF14, PABPC3, TEKT4)." (PMID 25528190, 2014).
FOXD4L1 also shares sentences with these, for which no sentence is quoted: cancer (2 papers).